LEP (leptin)
Diseases named in the same sentence as LEP in open-access papers (continued):
Sharing a sentence is not in itself a finding about the gene and the disease.
central precocious puberty (6 papers, 2018 to 2025). "This study was an attempt to examine the changes in serum levels of ghrelin and leptin after 12-weeks of aerobic training and gonadotropin releasing hormone agonist (GnRH) treatment in girls with central precocious puberty." (PMID 37735188, 2023). "On the other hand, another study showed no change in leptin levels at the 3rd and 6th months of GnRH analogue therapy in 37 girls with central precocious puberty." (PMID 38896175, 2025). "In a recent study from Thailand, 18 girls with central precocious puberty were followed up under GnRH analogue treatment for 20 weeks, resulting in no change in serum ghrelin and PYY levels, but a significant increase in leptin levels along with fat percentage." (PMID 38896175, 2025). "In this study, it was aimed to compare the circulating levels of ghrelin, leptin, PYY and NPY between the girls with idiopathic central precocious puberty (ICPP) and prepubertal girls, and also to evaluate the alterations in the levels of these hormones during leuprolide acetate treatment." (PMID 38896175, 2025).
cerebral malaria (6 papers, 2008 to 2025). A sequestration of Plasmodium falciparum in the brain, which can cause coma and/or seizures. "Conversely, in the context of infections like malaria, sequestration of infected red blood cells in the WAT drives leptin expression, which drives the development of cerebral malaria, increasing the risk of death." (PMID 39428707, 2025). "Leptin-deficient mice infected with P. berghei ANKA were shown to be resistant to the development of cerebral malaria whereas the normal mice developed signs of cerebral malaria." (PMID 30534129, 2018). "In human subcutaneous adipose tissue, parasite sequestration, phosphorylation of mTORC1, and local leptin production correlate with cerebral malaria mortality, despite unchanged circulating leptin levels." (PMID 39492784, 2024). "This study appears to provide the first indication that leptin-deficient ob/ob obese mice are permissive for the infection by Plasmodium berghei ANKA and resistant to cerebral malaria." (PMID 18489748, 2008). "Similarly, a reduction in leptin production under DR was shown to be responsible for enhanced survival from cerebral malaria, and these effects were mediated through reduced mTORC1 activity in T cells." (PMID 36399256, 2023). "Dietary restriction prevented severe experimental cerebral malaria (ECM) symptoms and death in mice through modulation of leptin levels and mechanistic target of rapamycin complex 1 (mTORC1) activity in T cells." (PMID 30534129, 2018). "In other experiments, injections of leptin were claimed to protect against TNF toxicity in ob/ob but not in +/+ mice; therefore, it is possible that leptin protects against cerebral malaria by damping down TNF-induced pathology." (PMID 18489748, 2008).
cerebrovascular disease (6 papers, 2012 to 2024). "Although this might be limited by the small statistical power due to the low number of cerebral infarcts in our study population, we must conclude that at present leptin and adiponectin cannot be considered predictive markers of cerebrovascular disease in this population." (PMID 38686200, 2024).
chondrosarcoma (6 papers, 2009 to 2022). A malignant cartilaginous matrix-producing mesenchymal neoplasm arising from the bone and soft tissue. "Our other research has identified that the adipokines resistin and leptin increase chondrosarcoma angiogenesis and metastasis via different miRNA–mRNA regulatory pathways." (PMID 36359873, 2022). "Leptin-dependent regulation of tube formation in endothelial progenitor cells was shown in a chondrosarcoma cell study." (PMID 33799880, 2021). "In chondrosarcoma, there is significant evidence that leptin can induce VEGF-C expression and its secretion, contributing to the lymphangiogenesis of human lymphatic endothelial cells by repressing miR-27b." (PMID 33799880, 2021). "We indicated that the leptin expression is highly correlated with tumor stage according to the IHC analysis of human chondrosarcoma tissues." (PMID 27345723, 2016). "To characterize the role of leptin in tumor lymphangiogenesis of chondrosarcoma, we first analyzed the expression profile of VEGF-C in specimens of chondrosarcoma patients." (PMID 27345723, 2016). "Our study is the first to describe the mechanism of leptin-promoted lymphangiogenesis by upregulating VEGF-C expression in chondrosarcomas." (PMID 27345723, 2016). "Here, we found that leptin promoted VEGF-C expression in chondrosarcomas and enhanced LECs lymphangiogenesis." (PMID 27345723, 2016). "Current study showed that leptin markedly repressed miR-27b expression in human chondrosarcoma cells in vitro and in vivo." (PMID 27345723, 2016). "Furthermore, we found that levels of leptin and VEGF-C in clinical specimens from patients with chondrosarcoma were correlated with tumor stage, implying that leptin may be a candidate prognostic indicator for chondrosarcoma progression." (PMID 27345723, 2016). "Thus, leptin could serve as a therapeutic target in chondrosarcoma metastasis and lymphangiogenesis." (PMID 27345723, 2016). "We further demonstrated that leptin promoted VEGF-C production and secretion in human chondrosarcoma cells." (PMID 27345723, 2016). "Here we indicate the clinical significance of leptin and VEGF-C in specimens of chondrosarcoma patients." (PMID 27345723, 2016). "We quantitated the IHC results and found the leptin and VEGF-C expression have high positive relationship in human chondrosarcoma patients." (PMID 27345723, 2016). "However, it is still not well-recognized whether leptin increases VEGF-C expression to facilitate tumor-associated lymphangiogenesis in human chondrosarcoma." (PMID 27345723, 2016). "Our results showed a clinical correlation between leptin and VEGF-C as well as tumor stage in human chondrosarcoma tissues." (PMID 27345723, 2016). "In present study, we examined the effect of leptin in VEGF-C-mediated lymphangiogenesis, and evaluated the involvement of miRNA in human chondrosarcoma cells." (PMID 27345723, 2016). "However, the effect of leptin on VEGF-C regulation and lymphangiogenesis in human chondrosarcoma has hugely remained a mystery." (PMID 27345723, 2016). "Leptin was shown to regulate the differentiation of the ATDC5 chondrogenic cell line through activation of ERK1/2, and to activate the IRS-1/PI3K/Akt pathway to induce migration of human chondrosarcoma cells." (PMID 20534145, 2010). "Transfection of JJ012 cells with OBRl AS-ODN but not MM-ODN inhibited leptin-increased VEGF-C expression, indicating OBRl involved leptin-increased VEGF-C production in human chondrosarcoma cells." (PMID 27345723, 2016).
chronic hepatitis C (6 papers, 2013 to 2021). "Serum leptin concentrations are also associated with fatigue severity in patients with chronic hepatitis C and irritable bowel syndrome." (PMID 23570606, 2013). "In HCC there are some established risk factors, including chronic hepatitis B, chronic hepatitis C, alcohol consumption, and NAFLD, all of them potentially linked to leptin." (PMID 34209386, 2021). "Furthermore, it has been shown that IL-1RA levels were positively correlated with serum leptin levels in ME/CFS and that leptin was associated with fatigue severity in patients with ME/CFS but also with chronic hepatitis C and irritable bowel syndrome." (PMID 33046133, 2020).
colorectal tumor (6 papers, 2011 to 2023). "It is of interest that even obese mice demonstrated a significant inhibition of colorectal tumor cell growth when they were genetically-derived to be deficient in either leptin or leptin-receptor." (PMID 24465801, 2014). "As adipocytokines, adiponectin and leptin play opposite roles in the proliferation and migration of colorectal tumor cells." (PMID 35668493, 2022). "Others found that leptin acts as a growth factor for colorectal tumors after initiation with AOM in mice." (PMID 26347815, 2015). "In present study, inhibition of Notch signaling by the γ-secretase inhibitor DAPT significantly reduced NOTCH1, JAGGED1, LEPTIN, ObRb, IL-1β, VEGF-A, and VEGFR1 mRNA levels in colorectal tumor tissues compared to control groups." (PMID 38152619, 2023). "The inhibition of leptin signaling by the leptin receptor antagonist Allo aca reduced NOTCH1, IL-1R, and ObRb mRNA levels in colorectal tumor tissues." (PMID 38152619, 2023). "The blockade of Notch signaling by the γ-secretase inhibitor DAPT significantly reduced NOTCH1, JAGGED1, LEPTIN, ObRb, IL-1β, VEGF-A, and VEGFR1 mRNA levels in colorectal tumor tissues." (PMID 38152619, 2023). "Therefore, the leptin signaling might be important for colorectal tumor growth." (PMID 22174655, 2011). "First, we determined whether Notch, IL-1, and leptin signaling could be involved in the regulation of NOTCH1, JAGGED1, LEPTIN, ObRb, IL-1β, IL-1R, VEGF-A, VEGFR1, and VEGFR2 gene expression in colorectal tumor tissues." (PMID 38152619, 2023). "Furthermore, inhibition of IL-1 signaling by Anakinra decreased NOTCH1, JAGGED1, IL-1β, LEPTIN, ObRb, VEGFA, VEGFR1, and VEGFR2 expressions in colorectal tumors." (PMID 38152619, 2023).
craniopharyngioma (6 papers, 2009 to 2025). A benign, partly cystic, epithelial tumor of the sellar region, presumably derived from Rathke pouch epithelium. "Hypothalamic damage in patients with craniopharyngioma leads to organic leptin resistance in the afferent arm and ANS dysfunction in the efferent arm, promoting inadequate energy expenditure and excessive energy storage." (PMID 33591998, 2021). "It has been also showed leptin concentrations in serum of patients with craniopharyngioma increased over proportionally when patients developed obesity." (PMID 21846381, 2011). "Significantly elevated leptin levels with respect to BMI were found in 11 craniopharyngioma patients who had been affected by a suprasellar tumour, whereas 3 patients with an intrasellar tumor had lower, almost normal serum leptin levels." (PMID 21846381, 2011). "Others have suggested that the higher-than-expected plasma leptin concentration for the body mass index (BMI) indicates a disturbed feedback control of leptin secretion due to the craniopharyngioma and/or surgery." (PMID 19341477, 2009). "This was also reported for 11 patients with a suprasellar craniopharyngioma, whereas 3 patients with intrasellar craniopharyngioma had lower, almost normal leptin concentrations." (PMID 19341477, 2009). "It has been suggested that the craniopharyngioma and/or surgery disturb the feedback control of leptin secretion." (PMID 19341477, 2009). "Roth, evaluating serum leptin levels in 14 patients after neurosurgical treatment for craniopharyngioma, suggested that the hypothalamic structures might be insensitive to endogenous leptin." (PMID 21846381, 2011).
cystic fibrosis (6 papers, 2016 to 2025). Autosomal recessive disorder caused by pathogenic variants in the CFTR gene (cystic fibrosis transmembrane conductance regulator), which encodes a chloride and bicarbonate channel expressed in epithelial cells, and follow the diagnosis criteria. "The relationship between lung function decline and nutritional status associates disease severity and elevated serum leptin levels in patients with cystic fibrosis." (PMID 41380738, 2025). "As in the general population, it has been shown that circulating leptin levels in cystic fibrosis are associated with percentage of body fat." (PMID 27293305, 2016). "However, it is still unknown whether circulating leptin levels are associated with low bone mineral density and fracture risk in cystic fibrosis." (PMID 40076690, 2025). "Thus, the role of leptin in the oncogenic transformation of cystic fibrosis requires further studies, especially including obese women with cystic fibrosis as well as normal weight and obese control groups." (PMID 27293305, 2016).
hypercoagulability (6 papers, 2015 to 2024). "From the other secreted proteins, PAI, IGF and leptin; PAI has been found to cause hypercoagulation." (PMID 32524217, 2020).
invasive ductal carcinoma (6 papers, 2013 to 2023). "DCIS, invasive ductal carcinoma and invasive lobular carcinoma histotypes showed more frequently low scores of leptin immunostaining while the vast majority of mucinous carcinomas were of high immunostaining scores." (PMID 29121911, 2017). "Furthermore, in our research we observed a tendency to significantly higher pre- and post-treatment leptin concentrations in invasive ductal carcinoma." (PMID 36556428, 2022). "Interestingly, we observed significantly higher concentrations of YKL-40 and leptin but a lower concentration of adiponectin in the group of patients with invasive ductal carcinoma with respect to their invasive lobular carcinoma counterparts." (PMID 32512860, 2020). "Interestingly, we observed significantly higher concentrations of YKL-40 and leptin (both p < 0.01), but a lower concentration of adiponectin (p < 0.001) in the group of patients with invasive ductal carcinoma with respect to their invasive lobular carcinoma counterparts." (PMID 32512860, 2020).
irritable bowel syndrome (6 papers, 2013 to 2025). Irritable bowel syndrome (IBS) is a chronic functional condition of the lower gastrointestinal (GI) tract characterized by abdominal pain or discomfort and disordered bowel habit (diarrhea, constipation, or fluctuation between the two). "Intraperitoneal administration of leptin to lean rats increased colonic epithelial permeability and altered zonula occludens-1 expression and organization, and the increased mucosal leptin may interact with mast cells and the nervous system to enhance diarrhea-predominant irritable bowel syndrome." (PMID 33167521, 2020).
joint disease (6 papers, 2016 to 2024). "In support of the clinical relevance of leptin in OA development, leptin serum levels 10 years prior to MRI assessment were associated with cartilage defects, bone marrow lesions, osteophytes, meniscal abnormalities, synovitis, and joint effusion in a population of middle-aged women." (PMID 31842972, 2019). "Studies suggest that leptin may act to regulate chondrocyte metabolism and has been related to the metabolic (non-mechanical load) effect of obesity on joint disease and could explain the association between joint disease and metabolic syndrome disorders." (PMID 30497420, 2018). "Leptin and anthropometric measurements may share pathways influencing clinical severity in KOA, but our results could indicate that WC may have a more important association than leptin in patients with joint effusion." (PMID 27629533, 2016). "As the role of adipokines in joint diseases has not been the subject of much investigation in veterinary medicine, we shall address adiponectin and leptin in more detail." (PMID 29769086, 2018). "Interaction between leptin and BMI in knee OA has been described previously using serum samples and related to radiologic KOA, but clinical severity was not evaluated, and this study was not controlled by the presence of inflammatory features such as joint effusion." (PMID 27629533, 2016).
liposarcoma (6 papers, 2017 to 2025). A usually painless malignant tumor that arises from adipose tissue. "PPARβ/δ was found to be highly expressed in liposarcoma compared to benign lipoma, and PPARβ/δ activation increased liposarcoma cell proliferation, which was mediated via the direct transcriptional repression of leptin by PPARβ/δ." (PMID 35954274, 2022). "An example of cell type-specific regulation of proliferation is the binding of PPARβ/δ to the leptin promoter, resulting in decreased leptin expression and increased liposarcoma cell proliferation." (PMID 29996502, 2018). "Furthermore, several lines of evidence suggest that PPARβ/δ and leptin signaling are interconnected, because neuronal-specific PPARβ/δ knockout mice are leptin resistant and downregulation of leptin upon PPARβ/δ activation have been seen in liposarcoma cells." (PMID 33924880, 2021). "To ensure the broader applicability of LEP and PTTG1 as classification biomarkers, we performed an independent validation using an external liposarcoma cohort (GSE30929)." (PMID 40407808, 2025). "The external dataset’s alignment with our findings underscores the potential of LEP and PTTG1 as reproducible biomarkers for prognosis and therapeutic stratification in liposarcoma." (PMID 40407808, 2025).
lymphedema (6 papers, 2012 to 2024). Excess fluid collection in tissues, causing swelling. "In support of this, higher serum leptin levels and dysregulation of the adipocytokine signalling pathway are associated with lymphedema, further strengthening the association of altered lipid transport and fat deposition within lymphedema." (PMID 36232660, 2022). "Extensive studies on the mechanisms of the identified microRNAs and association of leptin with arm lymphedema may provide new insights on the potential biomarkers for lymphedema that should be followed up in a prospective cohort study." (PMID 36232660, 2022). "Patients with lymphedema also express increased adiponectin and leptin in serum samples (and a reduced adiponectin/leptin ratio), outlining the potential hormonal pathway through which increased adiposity manifests within lymphatic patients." (PMID 38612716, 2024). "Nevertheless, expression of adiposity marker- leptin- was increased in lymphedema limb compared to both healthy subjects and healthy limb of LYM subject." (PMID 33854130, 2021). "Besides leptin, adipokines such as interleukin-6 have been reported to be increased in the serum in lymphedema patients to compensate for adipose tissue deposition as a response to chronic inflammation and lymphatic dysfunction." (PMID 36232660, 2022). "Considering the fact that the increase in BMI was probably partly due to coexisting lymphedema, the relative increase in leptin levels may even be more pronounced." (PMID 36432490, 2022). "Since increased serum levels of leptin in obese patients have been reported, we hypothesized that leptin has an important role in the pathogenesis of postoperative lymphedema in obese patients." (PMID 27366905, 2016). "However, the mechanisms by which postoperative lymphedema develops in obese patients and the mechanisms by which leptin regulates lymphatic endothelial cell homeostasis such as tube formation and cell proliferation remain unknown." (PMID 27366905, 2016). "Thus, regulating the level of leptin or IL-6 may be a viable strategy to reduce the incidence of postoperative lymphedema." (PMID 27366905, 2016). "In addition to weight control to reduce the serum level of leptin and leptin resistance, regulating the level of IL-6 may also be a viable strategy to treat postoperative lymphedema." (PMID 27366905, 2016). "Thus, regulating the level of leptin and/or IL-6 may reduce the incidence of postoperative lymphedema." (PMID 27366905, 2016). "In addition, the Luminex 51-plex features leptin; while the gene encoding leptin was not statistically upregulated in our discovery assay, we chose to include it in the serum protein analysis because if the central role of altered adipose biology in the natural history of human lymphedema." (PMID 23272198, 2012).
Multiple Organ Failure (6 papers, 2014 to 2023). A progressive condition usually characterized by combined failure of several organs such as the lungs, liver, kidney, along with some clotting mechanisms, usually postinjury or postoperative. "In addition, leptin and IL-17A may be useful as diagnostic biomarkers to identify multiple trauma patients at risk of developing multiple organ failure in an intensive care setting." (PMID 33931112, 2021). "The leptin concentration at time point 72 h was—according to the ROC curve analysis—a very good diagnostic marker for the discrimination between multiple trauma patients who developed multiple organ failure and the patients who did not." (PMID 33931112, 2021).